IL2 (interleukin 2)
Diseases named in the same sentence as IL2 in open-access papers (continued):
Sharing a sentence is not in itself a finding about the gene and the disease.
diabetes (continued). "In contrast, in patients with diabetes who had poorly controlled blood glucose levels, TNF-α, IFN-γ, IL-2, and IL-1β cytokine levels were increased in response to PPD." (PMID 31815150, 2019). "Our study also showed that the exogenous IL-33 leads to the expansion of CD11c+IL-2+ cells and increased number of CD4+Foxp3+ST2+ immunoregulatory cells that suppress the development of diabetes in mice treated with IL-33 during the induction of the disease." (PMID 30498495, 2018). "In addition, low dose IL-2 therapy that can selectively target Treg cells has shown positive outcomes in patients with Type 1 diabetes mellitus (DM) in clinical settings." (PMID 29073905, 2017). "When cytokine levels were measured 14 weeks after diabetes induction, a clear shift toward a Th1 pattern was present, characterized by higher IFN-γ and IL-2 secretion (respectively, p < 0.001) and lower IL-4 (p < 0.05) and IL-10 levels (p < 0.01)." (PMID 28851944, 2017). "The progression to diabetes in control NOD mice was characterized by significantly elevated levels of most Teff subsets (IFN-γ+, Th17+, IL-2+, TNF-α+ and CD40+ lymphocytes) in the pancreatic lymph node." (PMID 26674203, 2015). "Specifically, inflammatory cytokines such as interleukins IL-6, IL-2, and tumor necrosis factor-α (TNF-α) are elevated in hyperglycemia, suggesting that a chronic low grade inflammatory state exists in patients with diabetes." (PMID 24961298, 2014). "Correlation analysis showed that IL-2, IL-4, IL-7, EOTAXIN, and IFN-γ concentrations in tears were negatively correlated with duration of diabetes, i.e., the shorter the duration of diabetes the higher the cytokine concentration." (PMID 21203348, 2010). "In diabetic mice, low-dose IL-2 increased Foxp3+ cells in the retina compared with non-diabetic and diabetic controls (untreated diabetes: 3.01 ± 0.41 vs diabetes + low-dose Il-2: 5.90 ± 1.25 cells per field, p<0.001)." (PMID 40133487, 2025). "In the context of diabetes, our data, although not statistically significant, suggest that low-dose IL-2 tended to reduce HbA1c levels." (PMID 40133487, 2025). "In those diabetes participants where S‐specific T cells were detected, the response was unfocused, with the expected expression of IFNγ, TNF, and IL‐2, alongside a significant increase in the expression of the Th2 cytokine IL‐13 in S‐specific CD4+ and CD8+ T cells from both diabetes groups." (PMID 41367201, 2025). "The upregulation of CD73 with agents, including AGT-5, Aire-overexpressing DCs, Aspirin, BAFFR-Fc, CD4+ peptide, ICAs, IL-2 therapies, SAgAs, sCD73, stem cells, RAD51 inhibitor, TLR9 inhibitor, and VD, decreased the development of diabetes and atherosclerosis in preclinical trials." (PMID 39735551, 2024). "Blocking the CD28-B7 pathway or inhibiting IL-2 activity in non-obese diabetic (NOD) mice has shown to accelerate the development of diabetes." (PMID 39000278, 2024). "Regardless of diabetes status, the levels of IL-2 increased, while IL-28 decreased in the OND and OD groups." (PMID 39474247, 2024). "Our current study showed that low dose IL-2 treatment protected 50% mice from diabetes after STZ injection, which is a promising result but is not optimal when considering other treatment like IL-35 provided almost complete protection in STZ mice." (PMID 38424350, 2024). "The induction of diabetes mellitus leads to the initiation of the inflammatory process and the release of pro-inflammatory cytokines such as IL-2 and TNF-α and does not produce any change in the levels of IL-4, IL-5, and INF-ɣ." (PMID 37842429, 2023). "This strategy is a novel IL-2 drug design for biologic therapy using FA to alter the immunologic, pharmacokinetic, and biodistribution profile of IL-2; the same strategy has been successfully applied to semaglutide: a once per week GLP-1 agonist for treating diabetes and obesity." (PMID 36230665, 2022).
diabetes (continued). "It seems that diabetic patients diagnosed with SARS-CoV-2 infection had higher values of IL-2, IL-6, IL-10, and interferon gamma than those without diabetes mellitus (NDM) or impaired fasting glucose (IFG)." (PMID 34201473, 2021). "If diabetes prevention was the only criteria to evaluate the combined treatment versus treatment with IL-2:mAb complexes only, our approach seemingly did not lead to an improvement." (PMID 29802270, 2018). "hASC and hASC-CM treatments were able to normalize cytokine levels, as demonstrated by the IFN-γ and IL-2 decrease (p < 0.001 vs STZ) and IL-10 and IL-4 increase when treatments were performed 6 weeks after diabetes induction and cytokines measured 8 weeks later." (PMID 28851944, 2017). "Consistent with systematic IL-2, β-cell-specific IL-2 was sufficient to prevent the onset of diabetes long term at late preclinical stages but failed to induce remission in recent-onset diabetic NOD mice." (PMID 29033948, 2017). "Similarly, IOs suppressed IL-2 and IL-2R levels via inhibition of NF-κB in mice with STZ-induced diabetes." (PMID 28662169, 2017). "And IL-2 alone is not sufficient to prevent anti PDL1 mediated accelerated diabetes in case of the Idd3/10/18 strain." (PMID 24586872, 2014). "In the new-onset NOD mice previously cured by IL-2 therapy (at a dose of 2.5 × 104 IU/day), RAPA could even restore diabetes, despite the low doses and short period of its administration." (PMID 25322151, 2014). "There was one notable interaction between INS genotype and T1D status, however, in which antigen-specific T cells from control subjects with the diabetes-protective proinsulin VNTR III preferentially expressed IL-10, IL-2, and FASLG, genes known to participate in potent regulatory pathways." (PMID 24844227, 2014). "Regenerative processes have not been assessed as a mechanism for amelioration of diabetes in NOD mice with IL-2 immunotherapy." (PMID 24205242, 2013). "At this late stage after diabetes onset, Ab/IL-2 treatment was not sufficient to reverse hyperglycemia." (PMID 24205242, 2013). "Addition of IL-2 promoted Treg cell survival and protected NOD mice from diabetes." (PMID 19654878, 2009). "In humans, compared to the NOND group, the diabetes (obese or nonobese) groups exhibited negative correlations between adiponectin and IL-2 and IL-23, while showing positive correlations with ENA78, eotaxin, and IP-10, along with positive correlations between leptin and insulin and IL-23." (PMID 39474247, 2024). "This comparison demonstrated that diabetes may lead to an increase in the levels of IL-2 and TNF-α without altering the levels of IL-4, IL-5, and INF-ɣ (p>0.05)." (PMID 37842429, 2023). "Although in vitro studies of liver explants showed that low dose IL-2 increases activity of Tregs but not of Teff, clinical response is not completely predictable, and a worsening of disease has been observed in patients with diabetes." (PMID 31616649, 2019). "Similarly in Idd3/5.2 and Idd3/5.3 strains where the congenic Idd5.1 locus containing the CTLA4 gene is absent, IL-2 alone cannot prevent diabetes induced by PDL1 blockade." (PMID 24586872, 2014). "Furthermore, to assess the effect of Ab/IL-2 immunotherapy well after the development of diabetes, we tested the effect of delaying treatment for 4 weeks after diabetes onset, when beta cells were virtually absent." (PMID 24205242, 2013). "For instance, chronic non-infectious diseases such as diabetes mellitus, coronary artery disease, hypertension, and chronic obstructive pulmonary disease are known to lead to increased levels of cytokines (e.g., interleukin-2, tumor necrosis factor), which can induce depressive symptoms." (PMID 40110545, 2025). "Furthermore, co-culture with exenatide reduced the levels of IL-1β, IL-2, IL-17 and IFN-γ in human islet supernatants, disclosing that Th17 cell may be involved in GLP-1 related immuno-inflammatory modulation under diabetes context as well." (PMID 36463128, 2022).
diabetes (continued). "Accordingly, the administration of IL-2/JES6 after priming, but not before the transfer of self-reactive T cells, decreased the T-cell quorum for the induction of experimental diabetes." (PMID 36705564, 2023). "The total amounts of MIP-1α, IL-2, IL-6, IL-17, and TGF-β were significantly increased in the non-diseased sites of diabetes patients (p < 0.05), compared to those in the control group." (PMID 37835794, 2023). "(G, H) Diabetes was induced in Treg-depleted DEREG+ RIP.OVA mice (with DT) or Treg-replete DEREG+ RIP.OVA mice (without DT), which later received IL-2ic (IL-2/S4B6 or IL-2/JES6), or were left untreated (control)." (PMID 36705564, 2023). "The short-term neutralization of circulating IL-2 by anti-IL-2 monoclonal antibody reduces the number of Tregs in the periphery and elicits autoimmune gastritis in BALB/c mice and diabetes and other autoimmune manifestations in non-obese diabetic (NOD) mice." (PMID 22984435, 2012). "In one study, in a diabetic group, there was a decrease in the levels of IL-2, IL-10, IL-12, and TNF-α in contrast to a control group consisting of individuals without diabetes, which may be attributable to increased VEGF levels in the diabetic group." (PMID 38731110, 2024). "In an extension of these studies, it was observed that serum that contained TNF 75 U but not IL-1, IL-2, and IFN-γ (induced by OK-432 injection) when administered reduced the intensity of insulitis and inhibited the cumulative incidence of diabetes in NOD mice compared to the control." (PMID 28824543, 2017). "However, in the absence of Tregs, IL-2 produced by infiltrating CD4+ helper T cells activated NK cells and enhanced their IFN-γ production which leads to the onset of diabetes." (PMID 26220086, 2015). "At 6 h post-infection, IL-2 and GM-CSF were detected at higher concentrations, but there was a significant reduction of stimulated mononuclear cell production of IL-8, IL-10, IL-12p40, TNF-α, MCP-1, and MIP-1b in ESRD without diabetes group than in control group." (PMID 31875015, 2019).
type 1 diabetes (132 papers, 2006 to 2025). "Consistent with our finding of the protective effect of IL-2 signalling, we found that IL-6 signalling increased the risk of type 1 diabetes." (PMID 39271518, 2024). "The co-localisation of IL2RA expression in CD8+ effector memory T cells with type 1 diabetes risk is further supported by the previous reports of IL-2 impairment leading to CD8+ T cell exhaustion, potentially driven by both acute and chronic viral infections." (PMID 39271518, 2024). "In type 1 diabetes, NK cell is activated, which competed with Tregs for IL‐2, resulting in IL‐2 deprivation, Foxp3 down‐regulation and loss of Treg suppressive function." (PMID 32881301, 2020). "In this sense, it has been shown that Type I diabetes risk variants in the IL2 pathway genes are associated with microbial shifts in mice and humans, including the decrease of the Lachnospiraceae and Clostridiales families of the Firmicutes phylum." (PMID 32423041, 2020). "Our data also highlight the role of key Treg molecules, CTLA-4, CD25, IL-10 and IL-2, genetically associated with the development of type 1 diabetes, in the response to infection." (PMID 28815218, 2017). "Work from our lab has shown that disease susceptibility loci, such as CTLA-4 and IL-2, in Type 1 diabetes lead to Treg instability." (PMID 26834735, 2015). "Protective alleles in Idd3 reduce type 1 diabetes frequency and Il2 and Il21 are the prime candidate genes." (PMID 24586872, 2014). "A novel finding in this study was an association with several genes for IL-2 and IL-21 in chromosome 4q27, a region where SNPs associated with celiac disease and diabetes type 1 were also reported." (PMID 23843781, 2013). "We detected putatively causal type 1 diabetes risk genes using Mendelian Randomisation, and found that these were located disproportionately close to low priorityFDR signals (p = 0.005), as were genes in the IL‐2 pathway (p = 0.003)." (PMID 39749473, 2025). "This missense polymorphism changes arginine (R) to tryptophan (W) at position 620, impairing its interaction with the tyrosine kinase Csk, which enhances PTPN22 activation and decreases interleukin-2 production, thus increasing susceptibility to type I diabetes." (PMID 40565966, 2025). "Yet the use of lower doses of IL-2, with the underlying rationale that Treg cells would be more efficiently targeted than effector T cells, showed a preferential expansion of Treg cells both in preclinical models and in type 1 diabetes patients, which was associated with better prognostic markers." (PMID 30560927, 2018). "Given the key role that IL-2 signalling plays in maintaining FOXP3 expression, thereby maintaining Treg fitness, it has been postulated that many of the Treg-intrinsic defects observed in type 1 diabetes may be caused by a relative reduction in IL-2 signalling." (PMID 28770318, 2017). "In a HapMap-CEU population, a large block (480 kb) of linkage disequilibrium encompassing KIAA1109/Tenr/IL2/IL21 showed genetic associations with type 1 diabetes mellitus (T1DM), RA, juvenile idiopathic arthritis (JIA), psoriasis and psoriatic arthritis(PA)." (PMID 23889847, 2013). "Using co-localisation and Mendelian randomisation, we found genetic evidence to support the role of IL-2 and IL-6 signalling in the pathogenesis of type 1 diabetes." (PMID 39271518, 2024). "Much focus of immunotherapy for type 1 diabetes (T1D) has been devoted on selectively boosting regulatory T (Treg) cells using low dose IL-2 due to their constitutive expression of IL-2Rα, CD25." (PMID 38424350, 2024). "GNTI-122 is a dual-engineered Treg therapy product developed for the treatment of type 1 diabetes with enhanced stability, tissue specificity, and selective IL-2 signaling." (PMID 38516892, 2024). "In a model of type 1 diabetes, abatacept treatment combined with IL-2 administration had the beneficial effect of restoring regulatory T-cell homeostasis." (PMID 38567291, 2024).
type 1 diabetes (continued). "In conclusion, our results provide genetic evidence that IL-2, IL-6 and TYK2 signalling are associated with type 1 diabetes risk." (PMID 39271518, 2024). "Type 1 diabetes-associated variants of the human UBASH3A gene caused higher levels of gene expression and decreased NF-κB signaling and IL2 expression in CD4+ T cells." (PMID 38398001, 2024). "In a Phase I/II trial, researchers have identified the optimal dose of IL-2 for safely expanding Tregs in children with Type 1 Diabetes (T1D) (NCT01862120)." (PMID 39290699, 2024). "In Alvarez, we describe the immunoprotective role of the CD25-biased IL-2 SYNTHORINTM molecule SAR444336 which promotes the generation of functionally-adapted FoxP3+ TREG in a pre-clinical model of type 1 diabetes." (PMID 39704171, 2024). "A previous small study showed that rs12722495, which is in strong LD (r2=0.89) with our lead IL2RA eQTL and type 1 diabetes risk locus rs61839660 near IL2RA, decreased IL2RA expression in Tregs as well as their sensitivity to IL-2." (PMID 39271518, 2024). "Regardless of the possible mechanism, our findings support the rationale of conducting type 1 diabetes prevention trials with low-dose IL-2." (PMID 39271518, 2024). "Abnormalities in the structure of its receptor have been observed in type 1 diabetes and the disorder of IL-2 synthesis by effector T cells has been suggested as a factor in the pathogenesis of the disease." (PMID 36768715, 2023). "The type 1 diabetes-associated variants in UBASH3A in human CD4+ T cells resulted in higher levels of gene expression and decreased NF-kB signalling and IL2 expression." (PMID 37224769, 2023). "Recently, a combinational therapy of in vitro expanded polyclonal Tregs and low-dose IL-2 was tested in patients with type I diabetes in a phase I clinical trial." (PMID 36705564, 2023). "Recently, we have employed targeted single-cell multiomics to characterise the immune response to low-dose IL-2 immunotherapy in newly diagnosed type 1 diabetes patients from the DILfrequency study." (PMID 37700317, 2023). "Using a targeted single-cell multiomics approach, we have recently identified a prolonged anti-inflammatory gene expression signature in T and NK cells in type 1 diabetes patients treated with low-dose IL-2." (PMID 37700317, 2023). "These new IL-2 muteins resemble the biological function of IL-2/JES6-1 mab complexes with promising results in treatment of type I diabetes in a pre-clinical murine model." (PMID 36562079, 2023). "The percentage of CD3+CD4+ T lymphocytes with the intracellular expression of IFN-γ+, IL-2, IL-4, IL-10 and IL-17 in the patients with type 1 diabetes and in the control group was analyzed." (PMID 36768715, 2023). "Here we examine the effects of interval administration of low-dose recombinant IL-2 (iLD-IL-2) in type 1 diabetes using high-resolution single-cell multiomics and flow cytometry on longitudinally-collected peripheral blood samples." (PMID 36443294, 2022). "For example, low-dose IL-2 selectively activates Treg cells by activating IL-2/IL-2R signaling in type 1 diabetes." (PMID 36138890, 2022). "As for human therapy utilizing immunomodulatory effects of Tregs, induction of the Treg population with IL-2 has been successful in treating type 1 diabetes, alopecia areata, and hepatitis C virus-induced vasculitis." (PMID 38983511, 2022). "In preclinical models, low-dose IL-2 was able to expand Tregs and reverse established type 1 diabetes." (PMID 35156097, 2021). "It was found that the concentration of IL-2 in children with long duration type 1 diabetes was higher than in healthy subjects (p = 0.030)." (PMID 34830017, 2021). "The DILT1D trial was followed by the ‘Adaptive study of IL-2 dose frequency on regulatory T cells in type 1 diabetes (DILfrequency)’, to establish the optimal dose and frequency of aldesleukin administration." (PMID 32399500, 2020).